BDNF (brain derived neurotrophic factor)
Diseases named in the same sentence as BDNF in open-access papers (continued):
Sharing a sentence is not in itself a finding about the gene and the disease.
depression (continued). "Another study also showed that in rats, zinc deficiency-induced depression-like behaviors are associated with increased NMDAR (GluN2A and GluN2B), decreased PSD-95, p-CREB, and BDNF in the hippocampus." (PMID 37108261, 2023). "An inverse relationship between BDNF and depressive symptoms as observed in the third trimester suggests that late pregnancy is the period of greatest vulnerability to BDNF-induced depression." (PMID 37143780, 2023). "Human postmortem cerebella in depression show increases in Gsα localization in lipid rafts and decreases in BDNF expression." (PMID 36982638, 2023). "In this regard, we note that higher cortisol concentrations, lower BDNF concentrations, and disrupted sleep are considered reliable biomarkers of psychophysiological arousal and of symptoms of depression." (PMID 37763782, 2023). "The aim of this systematic review was to examine the bidirectional relationship between CVD and depression, focusing on the potential role of low serum BDNF levels in the development of either disease in the presence of the other." (PMID 37895349, 2023). "According to the neurotrophic theory, reduced BDNF expression deprives neurons of necessary nutrition, resulting in neuronal atrophy, decline in synaptic plasticity, and the onset of depression." (PMID 38026940, 2023). "The decreased levels of brain-derived neurotrophic factor (BDNF) during stress also trigger depression and sleep dysregulation leading to sleep deprivation or insomnia." (PMID 37163444, 2023). "The reserpine-induced pain-depression dyad model mice (0.97 ± 0.16) showed a significant decrease in the expression of BDNF mRNA in the brain cortex compared to the control group (2.5 ± 0.26)." (PMID 38259687, 2023). "Our results expand on those findings showing that reduced BDNF levels were similar to values in drug-free patients with depression." (PMID 37759825, 2023). "Ginsenoside Rb1, another active compound found in ginseng and water extract of Panax ginseng, has been shown to exert promising antidepressant-like effects in a depression model via the BDNF/TrkB-GSK-3β signaling pathway." (PMID 37047914, 2023). "The Pearson correlation was used to evaluate the correlation between anxiety and depression scores and serum BDNF, NT-3,5-HT levels in patients with MHD." (PMID 37750080, 2023). "Dysregulation of BDNF functions have many implications in terms of diseases such as obesity, anxiety, depression, and neurodegenerative diseases." (PMID 37238659, 2023). "The BDNF/CREB pathway is deeply involved in the development of psychiatric disorders such as depression, Alzheimer’s disease, Parkinson’s disease, bipolar disorder, and memory disorders." (PMID 37663268, 2023). "The most pertinent point is that pro-inflammatory cytokines such as IL-6 and TNF impair the expression of BDNF, which leads to the onset of depression." (PMID 36978923, 2023). "Several large studies done with human subjects delineate the utility of BDNF as a possible pharmacologic target or a biomarker for depression." (PMID 37242525, 2023). "The “BDNF theory” of depression results from preclinical studies demonstrating that several forms of stress reduce BDNF-mediated signalling in the hippocampus, whereas chronic treatment with antidepressants increases BDNF-mediated signalling." (PMID 36902200, 2023). "Recent studies highlight the roles of WNT and SHH signaling in depression and depression-like behaviors, possibly via BDNF-mediated processes." (PMID 37035502, 2023). "Hippocampus-derived brain-derived neurotrophic factor (BDNF) has been identified as a significant factor in the development of depression." (PMID 37089558, 2023). "Three of the six studies did not consider potential confounding variables for assessing the relationship between BDNF serum levels and depression." (PMID 37895349, 2023). "Some pieces of evidence suggested that serum BDNF levels are reduced in patients with depression and anxiety." (PMID 37012351, 2023).
depression (continued). "At the same time, E2 supplementation in such animals reverses the BDNF down-regulation and prevents the development of a depression-like phenotype." (PMID 36639604, 2023). "Only one study that investigated the possible role of altered BDNF levels in the development of depression in patients with coronary artery disease was included in this review." (PMID 37895349, 2023). "BDNF levels are significantly lower in patients with major depression than in healthy controls, and they recover after antidepressant treatment." (PMID 37089558, 2023). "Recent research has demonstrated that alterations in gut microbiota distribution, according to the brain-gut axis mechanism, can modulate BDNF expression, thereby influencing the onset of depression." (PMID 38259274, 2023). "BDNF, one of the Nrf2 target genes, has been found to exert antidepressant effects in behavioural models of depression." (PMID 37735410, 2023). "Activation of this receptor has a positive influence on cerebral neuroplasticity by increasing BDNF synthesis and increasing c-FOS factor expression in the anterior cingulate cortex and mPFC—areas of the brain implicated in depression." (PMID 36978872, 2023). "They report improvements in all subjective and objective sleep parameters, including depression scores, and increased blood serum levels of brain‐derived neurotrophic factor and norepinephrine." (PMID 37202368, 2023). "Brain-derived neurotrophic factor (BDNF) and its receptors have been found to participate in mechanisms of depression and antidepressant drugs’ action." (PMID 37761014, 2023). "Brain‐derived neurotrophic factor (BDNF) is a specific class of factors widely distributed in the brain that play an important role in depression and neurodegenerative diseases." (PMID 37909847, 2023). "The possible correlation between the coagulation system and the development of depression can be further discovered via the production of brain-derived neurotrophic factor (BDNF), as the tPA-plasmin pathway cleaves the precursor to BDNF, pro-BDNF, to BDNF." (PMID 37599890, 2023). "It reversed depression and pseudodementia by reducing corticosterone levels and increasing hippocampal BDNF, 5-hydroxytryptamine (5-HT), dopamine (DA), and acetylcholine (ACh) levels in male Wistar rats." (PMID 37299526, 2023). "For example, patients with major depressive disorder have lower serum BDNF levels than do healthy controls." (PMID 37761014, 2023). "Serotonergic receptors such as 5-HT2A have also been shown to modulate BDNF expression in limbic neurocircuits such as the prefrontal cortex and hippocampus, important in the context of major depressive disorder." (PMID 37631295, 2023). "Overall, these data confirm the results of other studies that suggest an involvement of BDNF in the pathogenesis of epilepsy and depression and those of our previous study." (PMID 38069144, 2023). "In IBD subjects in remission, the severity of depression symptoms was correlated positively with BDNF mRNA expression and negatively with BDNF protein concentration (r = 0.363, p = 0.038; r = −0.349, p = 0.046, respectively)." (PMID 36984890, 2023). "BDNF is one of the main members of the neurotrophic factor family, which is essential for neurogenesis and the pathogenesis of depression." (PMID 36829227, 2023). "Serum BDNF levels in patients with major depression are significantly lower than those in healthy individuals, and BDNF levels in severe patients are lower than those in moderate patients." (PMID 37509026, 2023). "In sum, the intricate relationship between oxidative stress and BDNF levels plays a significant role in the development and progression of depression and other neuropsychiatric disorders." (PMID 37631295, 2023). "Many studies have shown the connection between serum BDNF levels and anxiety and depression (Rahmani, Rahmani & Rezaei, 2020; Notaras & Van den Buuse, 2020)." (PMID 37750080, 2023).
depression (continued). "Several studies have reported that BDNF and its receptor, tropomyosin-related kinase B (TrkB), are involved in the pathogenesis and treatment of depression." (PMID 38105928, 2023). "The connection between the BDNF signaling pathway and major depressive disorder is extensively studied and holds great importance in advancing our understanding and treatment of this alarming disorder." (PMID 37631295, 2023). "Acupuncture appears to have a significant effect on the emergence of depression by boosting the production of the plasticity protein BDNF." (PMID 37780709, 2023). "While it is clear that proBDNF plays a role in depression, both proBDNF and mature BDNF were also increased after ECS in rats." (PMID 37174977, 2023). "Brain-derived neurotrophic factor (BDNF) has been studied as a biomarker of major depressive disorder (MDD)." (PMID 37834258, 2023). "Obesity damages leptin-induced regulation of BDNF expression and synaptogenesis, which is thought to be related to the onset of depression." (PMID 37387537, 2023). "For example, overexpression of the BDNF gene in the dorsal raphe nucleus (DRN) of obese and diabetic mice subjected to a stress-induced depression protocol will have an associated antidepressant effect by improving serotonin homeostasis." (PMID 38067196, 2023). "According to other authors, the activation of PPAR-γ relieves symptoms associated with cognitive dysfunctions and obesity, and improves the level of brain-derived neurotrophic factor (BDNF), which is reduced in depression and type 2 diabetes." (PMID 37049434, 2023). "Elevated levels of brain derived neurotrophic factor (BDNF) have been shown to alleviate symptoms of depression and anxiety and yield cognitive improvement." (PMID 37139329, 2023). "Researchers are constantly investigating the relationship between variations in activity and content of BDNF and the occurrence or outcome of depression." (PMID 37089920, 2023). "A few studies performed on adult subjects have proven that BDNF gene promoter methylation profile differs in the group of patients suffering from depression compared to the healthy control." (PMID 34590201, 2023). "For example, research has demonstrated that blocking BDNF in the NAc has an antidepressant-like effect, whereas microinjecting BDNF into the NAc results in a depression-like effect in the FST." (PMID 37895171, 2023). "For example, after a prolonged treatment with SSRIs, the methylation of promoter CpG sites of BDNF was considerably reduced, improving treatment and reducing depression scores after treatment." (PMID 37631295, 2023). "In the social defeat stress model of depression, BDNF was shown to be required for the development of social aversion using the viral-mediated, mesolimbic-dopamine-pathway-specific knockdown of BDNF." (PMID 37895171, 2023). "More studies on large samples are needed to verify the usefulness of serum BDNF and IL-6 as biomarkers of depression and antidepressant treatment response in children." (PMID 34590201, 2023). "Studies examining the role of BDNF in the relationship between CVD (other than stroke) and depression are needed along with those investigating the BDNF response to cardiac events." (PMID 37895349, 2023). "The relationship between BDNF and major depressive disorder is an extensive area of study with some inconsistencies between results and a lot to uncover." (PMID 37631295, 2023). "A study has shown that in rats, zinc deficiency-induced depression-like behaviors are associated with increased NMDAR (GluN1, GluN2A, GluN2B), decreased AMPAR(GluA1), p-CREB, and BDNF in the hippocampus to change the NMDAR neuronal signal." (PMID 37108261, 2023). "It was also shown that ADSC treatment enhanced the levels of BDNF and TrkB expression, which had previously been observed to be reduced following depression." (PMID 36986674, 2023).
depression (continued). "What is important, carotenoids have been tested for mechanisms in very important drug targets such as MAO or BDNF, known to be closely related to depression through molecular docking studies for possible inhibitory activity." (PMID 36978923, 2023). "In female mice, oxytocin administration reduces dexamethasone-induced depression-like symptoms through increasing hippocampus cAMP-response element binding protein (CREB)-BDNF signaling." (PMID 37631295, 2023). "We postulate that the synergic effect of depression and DM in downregulation of BDNF has led to a greater decline in serum BDNF levels." (PMID 36787304, 2023). "Anxiety and depression in patients with MHD are closely related to the levels of serum BDNF, NT-3, and 5-HT." (PMID 37750080, 2023). "On examining the role of BDNF in the development of depression after coronary artery disease (ACS), a different role of BDNF was identified in this study." (PMID 37895349, 2023). "A recent study showed that OSA patients with pronounced symptoms of depression had lower levels of BDNF and proBDNF in the morning compared to OSA individuals without mood disturbances." (PMID 36768132, 2023). "In summary, plasma BDNF is currently more suitable as a biological indicator of depression severity than as a biological indicator of suicidal ideation." (PMID 37509026, 2023). "Investigators have also evaluated the efficacy of utilizing Mediterranean diet to improvement plasma BDNF levels in patients diagnosed with depression." (PMID 36720792, 2023). "Loganin (10 and 20 mg/kg) and FH significantly reversed the mRNA and protein expression levels of BDNF in CUMS‐induced depression‐like mice, whereas 5 mg/kg loganin hardly reversed." (PMID 37408379, 2023). "The serum BDNF level in healthy individuals is approximately 1.2-fold higher than that in patients with depression." (PMID 38082356, 2023). "Improvements in mood (e.g., depression and anxiety) resulting from BA supplementation have been suggested to be related to changes in BDNF expression in the hippocampus." (PMID 36839281, 2023). "For example, physiological studies suggest that PA can improve elevated levels of pro-inflammatory cytokines and deficits in the production of brain-derived neurotrophic factor, considered as the pathophysiology of depression." (PMID 37635213, 2023). "Antidepressants modulate the brain‐derived neurotrophic factor (BDNF) and induce antidepressant‐like influence in short‐term behavioural depression models." (PMID 37799103, 2023). "The neurotrophin brain-derived neurotrophic factor (BDNF), which acts as a transducer, is responsible for improving cerebral stroke, neuropathic pain, and depression." (PMID 35821455, 2023). "Overexpression of SIK2 in the hippocampus induced depression-like behaviors, accompanied by attenuated BDNF signaling and neurogenesis, while knockdown of SIK2 produced antidepressant-like effects." (PMID 36731029, 2023). "Chronic treatment with Zn2+ was observed to increase BDNF levels in the hippocampus and cortex in rats, implying the potential involvement of Zn2+ in the depression via BDNF system." (PMID 37432243, 2023). "In brief, irisin and BDNF plasma levels are reduced in depressed subjects, and the direct brain infusion of irisin or BDNF has been shown to suppress depression-like behaviors in a similar fashion." (PMID 37834132, 2023). "This review focuses on the use of BDNF in the developmental assessment, treatment monitoring, and pharmacotherapy of selected diseases, with a particular emphasis on epilepsy, depression, anorexia, obesity, schizophrenia, and Alzheimer’s disease." (PMID 36831706, 2023). "Regardless of the BDNF level in different areas of the brain, the peripheral BDNF level is correlated with depression and the treatment response." (PMID 37396946, 2023). "It is well established that serum BDNF levels are reduced in depression and are normalised with treatment by antidepressants or PA." (PMID 36949894, 2023).
depression (continued). "BDNF expression has been shown to be significantly reduced in patients with depression, and several meta-analyses have revealed that patients with depression exhibit significantly reduced blood BDNF levels." (PMID 37719598, 2023). "Chronic restraint-stressed mice showed increased depression-like behavior and downregulation of the BDNF/TrkB signaling pathway." (PMID 37168717, 2023). "The discovery of a BDNF single nucleotide polymorphism (SNP) that leads to decreased processing and activity-dependent release of BDNF, namely Val66Met, has further aided in elucidating the significance of BDNF in depression and response to ketamine." (PMID 37614344, 2023). "Among those positively associated with depression are C-reactive protein, IL-6 and TNF-α while markers negatively associated with depression include KYNA, KYNA/3HK ratio, KYNA/QUIN ratio and BDNF." (PMID 37457896, 2023). "According to the only study included in our work that examined the relationship between CVD distinct from stroke and the occurrence of depression after coronary artery disease, the role of lower serum BDNF levels is rather uncertain." (PMID 37895349, 2023). "Correlation analysis between anxiety and depression scores and serum BDNF, NT-3, and 5-HT levels in MHD patients (x ́ ± s)." (PMID 37750080, 2023). "Peripheral BDNF indeed exerts tissue-repairing functions and is able to modulate the neuro-immuno-endocrine axis, implying the relevance of investigating it in depression." (PMID 37511930, 2023). "Converging data now suggest that deficits in BDNF lead to the pathogenesis of several diseases, such as depression, bipolar disorder, anxiety disorders, Huntington's disease, schizophrenia and Alzheimer's disease." (PMID 37909847, 2023). "Elderly patients with late-life depression displayed a similar reduction in serum BDNF that was significantly correlated with reduced hippocampal volume." (PMID 37174977, 2023). "BDNF is used in the developmental assessment, treatment monitoring, and pharmacotherapy of selected diseases, in particular epilepsy and depression, though two controversial views still exist that BDNF inhibits or promotes epileptogenesis." (PMID 38069144, 2023). "One study indicated that major depressive disorder patients had considerably reduced levels of BDNF pro-domain." (PMID 37780709, 2023). "As discussed in this review, some P1/P2Rs have been recognized as significant mediators of BDNF expression, which participate in multiple pathologies, including stroke, neuropathic pain, and even depression." (PMID 35821455, 2023). "In conclusion, exercise can improve depression by upregulating BDNF expression and promoting neurogenesis." (PMID 37239191, 2023). "It was observed that IF reduced anxiety and depression and increased neurogenesis markers BDNF and NT3 in the hippocampus, both in the control group and in DM2 rats; IF improved metabolic dysfunction and reduced corticosterone levels in rats with DM2." (PMID 37958535, 2023). "It is also known that depression is accompanied with decreased expression of BDNF and phosphorylated CREB (pCREB) in the hippocampus, whereas chronic antidepressant treatments reverse these molecular changes." (PMID 37603290, 2023). "BDNF can also be used as a biomarker of treatment response in patients with treatment‐resistant depression." (PMID 37909847, 2023). "The results in the hippocampal tissue revealed that compared with the control group, the mRNA and protein expression levels of BDNF were significantly decreased in CUMS‐induced depression‐like mice." (PMID 37408379, 2023). "A previous study found that the expression of BDNF was significantly decreased in patients with depression." (PMID 37509026, 2023). "Decreased levels of brain-derived neurotrophic factor (BDNF) are involved in the pathogenesis of depression." (PMID 36978872, 2023).